FBXL5 (F-box and leucine rich repeat protein 5)
Description:
Component of some SCF (SKP1-cullin-F-box) protein ligase complex that plays a central role in iron homeostasis by promoting the ubiquitination and subsequent degradation of IREB2/IRP2. The C-terminal domain of FBXL5 contains a redox-sensitive [2Fe-2S] cluster that, upon oxidation, promotes binding to IRP2 to effect its oxygen-dependent degradation. Under iron deficiency conditions, the N-terminal hemerythrin-like (Hr) region, which contains a diiron metal center, cannot bind iron and undergoes conformational changes that destabilize the FBXL5 protein and cause its ubiquitination and degradation. When intracellular iron levels start rising, the Hr region is stabilized. Additional increases in iron levels facilitate the assembly and incorporation of a redox active [2Fe-2S] cluster in the C-terminal domain. Only when oxygen level is high enough to maintain the cluster in its oxidized state can FBXL5 recruit IRP2 as a substrate for polyubiquitination and degradation. Promotes ubiquitination and subsequent degradation of the dynactin complex component DCTN1. Within the nucleus, promotes the ubiquitination of SNAI1; preventing its interaction with DNA and promoting its degradation. Negatively regulates DNA damage response by mediating the ubiquitin-proteasome degradation of the DNA repair protein NABP2.
Synonyms: FBL4; FBL5; FLR1; CC2D2A-AS1
Tractability: Small molecule: a structure with a bound ligand is known. PROTAC: UniProt records ubiquitination sites on it; ubiquitination databases record sites on it.
Gene: Protein-coding gene on chromosome 4 (15,604,381 to 15,681,679, reverse strand). Ensembl gene ENSG00000118564.
Subcellular location: Cytoplasm, perinuclear region; Nucleus
Pathways (Reactome):
Metabolism of proteins: Association of TriC/CCT with target proteins during biosynthesis; Neddylation
Immune System: Antigen processing: Ubiquitination & Proteasome degradation
Transport of small molecules: Iron uptake and transport
Gene Ontology:
Molecular function: iron ion binding; protein binding; ubiquitin-protein transferase activity
Biological process: intracellular iron ion homeostasis; protein ubiquitination; SCF-dependent proteasomal ubiquitin-dependent protein catabolic process; inorganic ion homeostasis; monoatomic cation homeostasis
Cellular component: nucleus; perinuclear region of cytoplasm; SCF ubiquitin ligase complex; cytosol; ubiquitin ligase complex
Genetic constraint (gnomAD): Loss-of-function variants: 19 observed, 63.11 expected, observed/expected ratio (o/e) 0.3, 90% interval 0.21 to 0.44. The upper end of that interval is the gene's LOEUF score, 0.44, which puts it in group 1 of 6, group 1 being the genes least tolerant of losing a copy. Missense variants: 654 observed, 765.52 expected, observed/expected ratio (o/e) 0.85, 90% interval 0.8 to 0.91. Synonymous variants: 273 observed, 264.74 expected, observed/expected ratio (o/e) 1.03, 90% interval 0.93 to 1.14.
Homologues: Orthologues: chimpanzee FBXL5 (99% identical), macaque FBXL5 (99% identical), pig FBXL5 (96% identical), dog FBXL5 (96% identical), rat Fbxl5 (94% identical), guinea pig FBXL5 (94% identical), mouse Fbxl5 (93% identical), rabbit FBXL5 (92% identical), tropical clawed frog fbxl5 (67% identical), zebrafish fbxl5 (56% identical), Drosophila melanogaster CG8272 (14% identical), Drosophila melanogaster CG9003 (13% identical), and 24 more. Paralogues in human: FBXL13 (15% identical), FBXL20 (14% identical), FBXL7 (13% identical), FBXL2 (13% identical), FBXL4 (12% identical), FBXL16 (11% identical), FBXL6 (11% identical), SKP2 (11% identical), FBXL17 (10% identical), FBXL19 (10% identical), FBXL14 (10% identical), FBXL3 (10% identical), and 3 more.
Diseases named in the same sentence as FBXL5 in open-access papers:
FBXL5 is named in the same sentence as 36 diseases in open-access papers, as found by Europe PMC text mining. Sharing a sentence is not in itself a finding about the gene and the disease. The quoted sentences say what the papers report.
cervical cancer (9 papers, 2017 to 2026). A primary or metastatic malignant neoplasm involving the cervix. "MiR-20 upregulation induces EMT and cisplatin resistance via F-box and leucine rich repeat protein 5/BTG anti-proliferation factor 3 (FBXL5/BTG3) signaling in cervical cancer HeLa and SiHa cell lines." (PMID 34003341, 2021). "Previous studies demonstrated that FBXL5 functions as a tumor suppressor in gastric and cervical cancers." (PMID 33142748, 2020). "The inhibitor of ankyrin repeats, SH3 domains, and proline-rich regions protein (iASPP), a key inducer of epithelial-mesenchymal transition (EMT), promotes cisplatin resistance by targeting FBXL5 and BTG3 through miR-20a in cervical cancer." (PMID 40534867, 2025). "Depletion of FBXL5 and B-cell translocation gene 3 (BTG3) enhances cell invasiveness and cisplatin resistance in cervical cancer." (PMID 40534867, 2025). "FBXL5 and FBXL14 also act as tumor suppressor genes in gastric cancer, cervical cancer, and head and neck cancer through degrading Snail1 and inhibiting EMT." (PMID 34249081, 2021). "In the research process, it has been reported that PPP1R13L promotes EMT through the microRNA-20a-FBXL5/BTG3 signaling pathway and endows cervical cancer cells with cisplatin resistance." (PMID 32508530, 2020). "In summary, SKP2 enhances EMT in breast cancer and melanoma, whereas FBXL5 suppresses EMT in human gastric and cervical cancer cells, and FBXL14 is an EMT inhibitor in head and neck cancer cells." (PMID 30999935, 2019). "The acquisition of EMT features represents a key contributor to chemoresistance in cervical cancer, thus the expression of the EMT repressors F-Box and Leucine Rich Repeat Protein 5 (FBXL5) and BTG Anti-Proliferation Factor 3 (BTG3) is retained low in cancer tissues and cisplatin-resistant cells." (PMID 33803151, 2021).
colon cancer (5 papers, 2019 to 2023). "FBXL5 is highly expressed in colon cancer, and its high expression has been associated with reduced overall survival and exaggerated clinicopathologic characteristics in colon cancer patients." (PMID 32429232, 2020). "In contrast to its tumor suppressor function in the liver and stomach, FBXL5 promotes colon cancer progression through regulation of the PTEN-PI3K-AKT signaling pathway." (PMID 32429232, 2020). "AM404, a metabolite of acetaminophen with antibacterial activity, was found to suppress the expression of FBXL5 and to inhibit the dedifferentiation and acquisition of stem-like properties in organoids of colon cancer patients, suggesting that this agent might have potential as an anticancer drug." (PMID 32429232, 2020). "Therefore, we have selected FBXL5 gene, which showed over three folds decrease upon AM404 treatment, functioned as an oncogene in the progression of colon cancer through regulating PTEN/PI3K/AKT signalling and HIF-1α transcriptional activity." (PMID 31906201, 2019).
gastric cancer (5 papers, 2017 to 2025). A primary or metastatic malignant neoplasm involving the stomach. "In gastric cancer, loss of FBXL5 increases cisplatin resistance by activating the Erk and p38 signaling pathways." (PMID 40534867, 2025). "Additionally, FBXL5 binds to RhoGDP dissociation inhibitor beta (RhoGDI2), reducing RhoGDI2-mediated cisplatin resistance in gastric cancer cells." (PMID 40534867, 2025). "Furthermore, FBXL5, another F-box protein, was reported to attenuate RhoGDI2-induced cisplatin resistance in gastric cancer cells." (PMID 28117675, 2017). "FBXL5 inhibits EMT and attenuates the metastasis and cisplatin resistance in gastric cancer." (PMID 28399926, 2017).
osteosarcoma (3 papers, 2022 to 2023). A usually aggressive malignant bone-forming mesenchymal neoplasm, predominantly affecting adolescents and young adults. "Furthermore, the activation of GPER1 had also been found to inhibit the migration and invasion of osteosarcoma cells through FBXL5-mediated post-translational downregulation of Snail." (PMID 37921845, 2023). "The results showed that the mRNA expression level of four ubiquitin-related genes (CORO6, UBE2L3, FBXL5, DNAI1) was significantly increased in osteosarcoma tissues as compared with adjacent normal tissues." (PMID 36060009, 2022). "The expression of ubiquitin-related genes (CORO6, UBE2L3, FBXL5, DNAI1, and DCAF8) showed an obvious significance in normal and osteosarcoma tissues." (PMID 36060009, 2022). "Likewise, DCAF8 lncRNA-associated mRNA, DCAF8, is a ubiquitin-related gene that decreased in osteosarcoma tissues, and together with other ubiquitin-related genes (CORO6, UBE2L3, FBXL5, DNAI1) seem to play a significant role in the clinical outcome of osteosarcoma." (PMID 36831395, 2023).
breast carcinoma (2 papers, 2021 to 2022). "Nevertheless, how and whether circRNA F-box and leucine-rich repeat protein 5 (circFBXL5) regulates the 5-FU resistance of breast cancer is uncertain." (PMID 34281530, 2021).
colorectal cancer (2 papers, 2019 to 2026). A primary or metastatic malignant neoplasm that affects the colon or rectum. "Based on our results, we conclude that AM404 as a new compound and FBXL5 as an associated key target gene with high therapeutic pharmacological potential could be used against human colorectal cancer and other infectious diseases." (PMID 31906201, 2019). "Therefore, we initially sought to examine whether the expression of FBXL5 was altered in patients’ colorectal cancers." (PMID 31906201, 2019).
hepatocellular carcinoma (2 papers, 2021 to 2024). A malignant tumor that arises from hepatocytes. "It was also found that excessive iron accumulation in the liver resulting from F-box and leucine-rich repeat protein-5 (FBXL5) ablation increases the risk of hepatocellular carcinoma (HCC) progression." (PMID 38999951, 2024). "The third-ranked most statistically significant miRNA upregulated in the TME cells, miR-1306, is known to target FBXL5 to promote the metastasis of a hepatocellular carcinoma through suppressing the snail degradation." (PMID 34062897, 2021).
iron deficiency (2 papers, 2023). "In the case of IRP2, the cellular iron availability signals degradation of the protein, which is, thus, only active under conditions of iron deficiency, or other conditions in which the FBXL5-dependent degradation system is inhibited." (PMID 37762610, 2023). "Interestingly, FBXL5 can bind iron in its C-terminal domain and the redox-sensitive 2Fe-2S cluster in its N-terminal domain: iron deficiency and/or changes in oxygen tension mediate FBXL5 destabilization and thus IRP2 stability." (PMID 36835406, 2023).
myelodysplastic syndrome (2 papers, 2017 to 2019). A clonal hematopoietic disorder characterized by dysplasia and ineffective hematopoiesis in one or more of the hematopoietic cell lines. "Transcriptomic analysis shows abnormal activation of oxidative stress responses and the cell cycle in FBXL5-deficient mouse HSCs as well as downregulation of FBXL5 expression in HSCs of patients with myelodysplastic syndrome." (PMID 28714470, 2017).
acute liver failure (1 paper, 2025). Rapid deterioration of liver function causing encephalopathy and coagulopathy. "Moreover, they also showed that liver-specific deletion of Fbxl5 resulted in dysregulation of iron homeostasis, leading to the development of steatohepatitis, and that these mice died with acute liver failure when fed a high-iron diet." (PMID 40710531, 2025).
acute lymphoblastic leukemia (1 paper, 2022). Leukemia with an acute onset, characterized by the presence of lymphoblasts in the bone marrow and the peripheral blood. "ALPK1, ACTN4, CALR, ZNF695, and FBXL5 were identified as novel prognostic genes in relapsed acute lymphoblastic leukemia." (PMID 36139553, 2022).
cervical adenocarcinoma (1 paper, 2017). An adenocarcinoma arising from the cervical epithelium. "Furthermore, we provided the first evidence that iASPP stimulates EMT and induces cisplatin resistance in both cervical adenocarcinoma cell line HeLa and cervical squamous cell carcinoma cell line SiHa, through regulating the downstream miR-20a-FBXL5/BTG3 signaling pathway." (PMID 28399926, 2017).
diabetes (1 paper, 2013). "There was a small (median differences = 0.01-0.04) but highly significant increase of DNA methylation in females compared to males in FBXL5 and CACYBP (p < 1.00E-04) and a trend towards significance for SCMH1 (p = 0.07), in the diabetes study where samples of both sexes were included." (PMID 23356856, 2013).
glioma (1 paper, 2021). A benign or malignant brain and spinal cord tumor that arises from glial cells (astrocytes, oligodendrocytes, ependymal cells). "The western blot results showed no significant alterations in the levels of FBXL5 nor IRP2 in our glioma cell lines." (PMID 33420375, 2021).
hereditary spastic paraplegia (1 paper, 2011). Hereditary spastic paraplegias (HSP) comprise a genetically and clinically heterogeneous group of neurodegenerative disorders characterized by progressive spasticity and hyperreflexia of the lower limbs. "Lastly, target gene searches for another movement disorder called Hereditary spastic paraplegia (HSP) resulted in identification of a disease gene at the 4p16-p15 locus (SPG 38,), which is near a new E3 ubiquitin ligase called F-box and leucine-rich repeat protein 5 (FBXL5, 4p15.32)." (PMID 22003390, 2011).
Immunodeficiency (1 paper, 2022). Failure of the immune system to protect the body adequately from infection, due to the absence or insufficiency of some component process or substance. "FBXL5−/− mice failed to sense intracellular iron levels and died in utero at embryonic day 8.5 as a result of iron overload and subsequent oxidative stress, whereas HOIL-1−/− mice exhibited amylopectin-like deposits in the myocardium, pathogen-specific immunodeficiency." (PMID 35490179, 2022).
liver cancer (1 paper, 2021). An epithelial or non-epithelial malignant neoplasm that arises from the liver. "Similarly, studies have reported that FBXL5 also plays a crucial role in tumor suppression in gastric and liver cancers via the maintenance of iron homeostasis." (PMID 34733841, 2021).
motor neuron disease (1 paper, 2011). "Taken together, these genetic data suggest that both IRPs and FBXL5 are located near loci thought to contain human motor neuron disease genes." (PMID 22003390, 2011).
neuroblastoma (1 paper, 2019). Neuroblastoma (NB) is the most common solid, extracranial childhood tumor. "Our results suggest that FBXL5 is involved in the degradation of IRP2 under oxidative stress in dopaminergic-like neuroblastoma cells, which implies that its role in the neuronal regulation of IRP2 in neurodegenerative diseases." (PMID 30760976, 2019). "In conclusion, we present novel evidence that the oxidative generators H2O2 induced an increase of FBXL5-mediated ubiquitination degradation in dopaminergic-like neuroblastoma cells." (PMID 30760976, 2019).
pancreatic cancer (1 paper, 2021). "After identifying FBXL5, SLC25A28, and SLC25A37 as substrate RNAs of ALKBH5, we further investigated the relevant mechanism associated with pancreatic cancer progression." (PMID 34733841, 2021). "Thus, we deduce that the protective role of ALKBH5 in pancreatic cancer is closely related to FBXL5-mediated regulation of iron metabolism." (PMID 34733841, 2021). "Mechanistically, the RNA stabilities of FBXL5 and SLC25A28, and the AS of SLC25A37 were affected, which led to their upregulation in pancreatic cancer cell line." (PMID 34733841, 2021). "Accordingly, we found that in pancreatic cancer cells, ALKBH5-overexpression led to reduction of intracellular iron levels, and this could be restored via FBXL5 knockdown." (PMID 34733841, 2021). "Combining the downregulation of FBXL5 in pancreatic cancer samples and its positive correlation with survival, our results indicate that FBXL5, as a downstream target of ALKBH5, plays a vital role in protecting against pancreatic cancer." (PMID 34733841, 2021).
pulmonary fibrosis (1 paper, 2024). Chronic progressive interstitial lung disorder characterized by the replacement of the lung tissue by connective tissue, leading to progressive dyspnea, respiratory failure, or right heart failure. "In our study, FBXL5 levels were considerably decreased in AECII from pulmonary fibrosis mice and BLM-injured MLE-12 cells." (PMID 38773980, 2024). "FBXL5 protein levels in AECII are substantial reduced in both BLM-induced pulmonary fibrosis mouse lung tissue and BLM-12 cells damaged by BLM." (PMID 38773980, 2024). "Therefore, further studies targeting FBXL5 regulation to control AECII mitochondrial iron deposition during lung fibrosis are required." (PMID 38773980, 2024). "Moreover, we found that the activation of the EP4 receptor negatively regulates the IREB2-MFRN2 axis by increasing FBXL5 expression, ultimately reducing mitochondrial iron deposition in AECII and potentially offering a treatment strategy for pulmonary fibrosis." (PMID 38773980, 2024). "Furthermore, our study showed that EP4 receptor activation considerably increased FBXL5 levels and effectively blocked the IREB2-MFRN2 axis, thereby reducing AECII mitochondrial iron deposition and attenuating fibrosis severity in BLM-induced pulmonary fibrosis mice." (PMID 38773980, 2024).
refractory anaemia (1 paper, 2017). "Expression of FBXL5 was significantly downregulated in the CD34+ cells of patients with refractory anaemia with ringed sideroblasts (RARS), a subgroup of MDS characterized by iron deposition and apoptosis in hematopoietic progenitor cells." (PMID 28714470, 2017).